LIPT1 (lipoyltransferase 1)
Diseases named in the same sentence as LIPT1 in open-access papers (continued):
Sharing a sentence is not in itself a finding about the gene and the disease.
Leigh disease (7 papers, 2013 to 2023). "Apart from secondary pyruvate dehydrogenase complex deficiency and fatal lactic acidosis, LIPT1 deficiency was also the cause of Leigh disease." (PMID 37435496, 2023). "LIPT1 deficiency was reported in embryonic demise, early death or Leigh-like encephalopathy, such as early infantile epileptic encephalopathy, Leigh disease, secondary pyruvate dehydrogenase complex deficiency, fatal lactic acidosis." (PMID 35837286, 2022). "Mutations in LIPT1 were found to cause some inherited metabolic disorders, such as a Leigh disease with secondary deficiency for pyruvate and alpha-ketoglutarate dehydrogenase and a fatal disease related to a specific lipoylation defect of the 2-ketoacid dehydrogenase complexes." (PMID 35837286, 2022). "Mutations in the LIPT1 gene were indicated to cause some genetic disorders, such as a Leigh disease with secondary deficiency for pyruvate and alpha-ketoglutarate dehydrogenase and a fatal disease related to a specific lipoylation defect of the 2-ketoacid dehydrogenase complexes." (PMID 36195876, 2022). "LIPT1 genetic alterations, including mutation and deep deletion, cause a variety of human diseases, such as Leigh disease and nonketotic hyperglycinemia with early-onset convulsions." (PMID 36330439, 2022). "Recessive variants in LIPT1 and LIPT2 can induce a variety of clinical range of disorders from Leigh syndrome to non-ketotic hyperglycemia, hypotonia, seizures, microcephaly, psychomotor retardation, and cardiomyopathy." (PMID 33426505, 2020).
lung carcinoma (6 papers, 2022 to 2025). "In summary, o8G-modified circKIAA1797 inhibits cellular cuproptosis through FDX1, LIPT1 and the mPTP and promotes lung cancer development." (PMID 40176113, 2025). "CircKIAA1797 binds to the signal transducer and activator of transcription 1 (STAT1) protein to inhibit the expression of lipoyltransferase 1 (LIPT1) in lung cancer cells." (PMID 40710359, 2025). "LIPT1, an enzyme that activates 2-ketoacid dehydrogenases related to the TCA cycle and promotes cuproptosis, has been reported the association with the prognosis of urothelial carcinoma and lung cancer in the Pathology Atlas project." (PMID 37152283, 2023). "In addition to CDKN2A, genes, including DLD, LIPT1, GLS, PDHB, and PDHA1, also have significant CNVs, indicating the heterogeneity of lung cancer tissue." (PMID 36712848, 2022).
bladder cancer (5 papers, 2022 to 2024). "LIPT1 inhibited cell migration in bladder cancer cell lines and contributed to favorable survival in bladder cancer patients." (PMID 38671021, 2024). "Most copper induced cell death genes were downregulated in various cancers, such as FDX1 in cholangiocarcinoma (CHOL); LIAS and LIPT1 in bladder cancer (BLCA); PDHB in glioblastoma (GBM) and kidney chromophobe cancer (KICH)." (PMID 36581992, 2022). "Chen found that LIPT1 may be a prognostic-related gene for bladder cancer, and then found that this gene has a certain degree of inhibitory effect on the migration ability of bladder cancer cells by transwell method." (PMID 36341437, 2022).
glioma (5 papers, 2022 to 2025). A benign or malignant brain and spinal cord tumor that arises from glial cells (astrocytes, oligodendrocytes, ependymal cells). "In glioma patients, the levels of CDKN2A, FDX1, DLD, DLAT, LIAS, LIPT1, and PDHA1 were significantly associated with the OS, disease-specific survival, and progression-free interval." (PMID 36579333, 2022). "Further analysis of the relationship between CRGs and the prognosis of gliomas revealed that high expression of FDX1, DLD, DLAT, and LIPT1 was associated with poorer survival in glioma patients, and high expression of CDKN2A and PDHA1 was significantly associated with better survival in gliomas." (PMID 36915038, 2023). "Furthermore, Cox regression analysis in the TCGA database showed that FDX1, LIPT1, DLD, DLAT, SLC31A1, ATP7A, and DLST might be risk factors; however, LIAS, ATP7B, and GCSH were significant preventive factors for gliomas." (PMID 37515314, 2023). "The expression of GLS (p < 0.001), LIPT1, FDX1, SLC31A1 (p < 0.01), DLST, CDKN2A, PDHA1, ATP7A, ATP7B, and NFE2L2 (p < 0.05) was different between glioma and adjacent tissues." (PMID 36936439, 2023). "Only GLS and ATP7B had low expression levels in glioma patients; however, others, including FDX1, LIPT1, DLD, and SLC31A1, were overexpressed." (PMID 37515314, 2023). "The expression levels of FDX1 and LIPT1 varied in different histological grades of glioma, as the glioma grade was increased, there was an upward trend of FDX1 and LIPT1 expression." (PMID 36915038, 2023). "Furthermore, cuproptosis-related genes (LIPT1, FDX1, and DLAT) have emerged as therapeutic targets in epilepsy and gliomas, underscoring its broad relevance." (PMID 41214704, 2025). "For OS outcomes of glioma patients, a 9-gene signature was selected to construct the prognostic score using their regression coefficients: Riskscore = (0.8949)*FDX1 + (0.4902)*DLD + (0.0778)*DLAT + (-0.9324)*LIAS + (0.1132)*GLS + (0.903)*LIPT1 + (-0.1847)*MTF1 + (-0.2352)*PDHA1 + (-0.2045)*PDHB." (PMID 36915038, 2023).
osteosarcoma (5 papers, 2022 to 2025). A usually aggressive malignant bone-forming mesenchymal neoplasm, predominantly affecting adolescents and young adults. "We demonstrated that LIPT1 knockout leads to HR repair defect in established osteosarcoma cell line (U2OS) and HEK-293 HR reporter cell lines." (PMID 40073141, 2025). "in addition, the protein expression level of LIPT1 was significantly elevated in both 143B and U2OS, and the protein expression level of FDX1 was significantly overexpressed in three osteosarcoma cell lines HOS, 143B, and U2OS." (PMID 35967366, 2022).
colorectal cancer (4 papers, 2022 to 2025). A primary or metastatic malignant neoplasm that affects the colon or rectum. "Notably, the expression level of LIPT1 (lipoyltransferase 1) is positively correlated with the risk score of colorectal cancer." (PMID 40276654, 2025). "The study revealed that, compared to normal tissues, genes FDX1, DLD, DBT, DLST, and DLAT were significantly downregulated in colorectal cancer tissues, while LIPT1, GCSH, and ATP7B genes were upregulated." (PMID 40276654, 2025). "It was found that the mutation frequency of each regulator is relatively low, of which ATP7A showed the highest mutation rate, followed by ATP7B and LIPT1, while FDX1, CDKN2A, SLC31A1, and GCSH showed no mutation in all colorectal cancer tissues." (PMID 36248908, 2022).
liver cancer (4 papers, 2023 to 2024). An epithelial or non-epithelial malignant neoplasm that arises from the liver. "Research in the field of liver cancer has made rapid progress, with studies constructing prognostic models and verifying that copper death‐related gene LIPT1 may promote the proliferation, invasion, and migration ability of liver cancer cells." (PMID 38898987, 2024). "Another study found that knocking out the lipoyltransferase 1 (LIPT1) inhibited the proliferation and invasion of liver cancer cells, suggesting that LIPT1 might be a new therapeutic target for liver cancer." (PMID 37665670, 2023). "In light of this background, it is pertinent to inquire, through bioinformatics and subsequent basic experimental validation, we have learned that in numerous cancer types, including liver cancer, LIPT2, LIPT1, and LIAS, which act as precursors for ALA synthesis, exhibit oncogenic activity." (PMID 39199143, 2024).
pancreatic cancer (4 papers, 2022 to 2025). "In this study, we successfully used cuprotosis-related genes to establish a prognosis-related risk model for pancreatic cancer patients, which included three genes LIPT1, LIAS, and DLAT." (PMID 36117848, 2022). "We discovered that elevated LIPT1 expression was associated with a worse prognosis in pancreatic cancer patients." (PMID 36035166, 2022). "Then Capan-1 and CFPAC-1 pancreatic cancer cell lines were selected for further experiments on LIPT1." (PMID 40367233, 2025). "WB indicated that the expression of LIPT1 were significantly elevated in pancreatic cancer cell lines (Capan-1, CFPAC-1 and COLO357) compared to normal pancreatic cells (HPDE6-C7)." (PMID 40367233, 2025). "The expression of 5 CRGs exhibited significant differences in PC cell lines and tissues, LIPT1-knockdowning inhibited proliferation and invasion of pancreatic cancer cell lines." (PMID 40367233, 2025). "CCK-8 and colony formation assays elucidated that LIPT1 knock downing markedly restricted the proliferation of pancreatic cancer cell lines." (PMID 40367233, 2025). "Firstly, the protein expression of LIPT1 in pancreatic cancer cell lines was teste." (PMID 40367233, 2025). "LIPT1 may promote proliferation, invasion and migration of pancreatic cancer cell lines." (PMID 40367233, 2025). "Finally, the function of LIPT1 in pancreatic cancer cell lines were validated by knocking down its expression level, which might promote proliferation, invasion and migration of pancreatic cancer." (PMID 40367233, 2025). "In addition, LIPT1 may promote proliferation, invasion and migration of pancreatic cancer cell lines." (PMID 40367233, 2025). "We selected a normal human pancreatic ductal epithelial cell line (i.e., HPDE6-C7) and 4 pancreatic cancer cell lines (i.e., CFPAC-1, PANC-1, SW1990, and AsPC-1) to examine the expression of DLAT, LIPT1, and LIAS." (PMID 36090999, 2022).
urothelial carcinoma (4 papers, 2022 to 2025). A malignant neoplasm derived from the transitional epithelium of the urinary tract (urinary bladder, ureter, urethra, or renal pelvis). "In recent years, LIPT1 has been reported to be a gene that may be associated with good prognosis in patients with urothelial carcinoma." (PMID 36818726, 2022).
epilepsy (3 papers, 2022 to 2025). A brain disorder characterized by episodes of abnormally increased neuronal discharge resulting in transient episodes of sensory or motor neurological dysfunction, or psychic dysfunction. "In addition, human LIPT1 deficiency cause epilepsy, metabolic abnormalities, and developmental delay." (PMID 37435496, 2023). "LIPT1 deficiency can cause developmental delays, epilepsy, and broad metabolic abnormalities." (PMID 36276933, 2022).
osteoarthritis (3 papers, 2024). A noninflammatory degenerative joint disease occurring chiefly in older persons, characterized by degeneration of the articular cartilage, hypertrophy of bone at the margins and changes in the synovial membrane. "Similarly, research has found that LIPT1 expression is significantly increased in the synovium of osteoarthritis, making it a potential key gene or therapeutic target for immune infiltration related to cuproptosis." (PMID 39730319, 2024). "Additionally, five genes related to cuproptosis (FDX1, LIPT1, PDHA1, PDHB, and CDKN2A) are considered candidate biomarkers or therapeutic targets for osteoarthritis synovitis." (PMID 39360273, 2024).
Sepsis (3 papers, 2024 to 2025). Sepsis is defined as life-threatening organ dysfunction caused by a dysregulated host response to infection. "Next, six key DECuGs (ANKRD9, DLD, LIPT1, MTF1, PDHB, UBE2D4) were identified as diagnostic biomarkers based on the two machine learning algorithms, suggesting their potential functional importance in the pathogenesis of sepsis." (PMID 38495196, 2024). "Finally, the 6 DECuGs (ANKRD9, DLD, LIPT1, MTF1, PDHB, UBE2D4) as diagnostic biomarkers for sepsis were identified by the intersection of the two machine learning algorithms." (PMID 38495196, 2024). "Furthermore, GSE236713 cohort was utilized to verify SLC31A1, MTF1, LIAS and LIPT1 level in sepsis." (PMID 39652607, 2024). "For immune cells, monocytes, T cells, B cells, and NK cells were related to DLD, LIPT1, MTF1, PDHB and UBE2D4 in the sepsis group." (PMID 38495196, 2024).
acute myelocytic leukemia (2 papers, 2022 to 2025). "In addition, the results demonstrated that LIPT1 expression was negatively related with cell cycle and DNA damage in acute myelocytic leukemia (AML)." (PMID 36330439, 2022). "Meanwhile, we found the up-regulated LIPT1 in lymphoid neoplasm diffuse large B-cell lymphoma (DLBC), acute myeloid leukemia (LAML), brain lower grade glioma (LGG) and thymoma (THYM)." (PMID 36330439, 2022).
acute myocardial infarction (2 papers, 2024 to 2025). Necrosis of the myocardium, as a result of interruption of the blood supply to the area. "In contrast, patients with acute myocardial infarction exhibit decreased levels of LIAS, PDHB, LIPT1, DLAT, and GLS, along with increased MTF1 levels." (PMID 39360273, 2024).
cerebral infarction (2 papers, 2022 to 2023). An ischemic condition of the brain, producing a persistent focal neurological deficit in the area of distribution of the cerebral arteries. "Our study revealed that the protein and mRNA expression levels of LIPT1 were lower in the post-LTx group than in the pre-LTx group via dataset analysis and animal experiments, which is consistent with the findings in a cerebral infarction model." (PMID 38074089, 2023). "We found that LIPT1 was downregulated in cerebral infarction and negatively correlated with NLRP3." (PMID 36818726, 2022).
cholangiocarcinoma (2 papers, 2022). A carcinoma that arises from the intrahepatic biliary tree (intrahepatic cholangiocarcinoma) or from the junction, or adjacent to the junction, of the right and left hepatic ducts (hilar cholangiocarcinoma). "Conversely, LIPT1 expression was significantly up-regulated in some other tumors, including cholangiocarcinoma (CHOL), colon adenocarcinoma (COAD), esophageal carcinoma (ESCA), glioblastoma multiforme (GBM), liver hepatocellular carcinoma (LIHC) and stomach adenocarcinoma (STAD)." (PMID 36330439, 2022).
diffuse large B-cell lymphoma (2 papers, 2022). "However, a large majority of cuproptosis-associated genes including FDX1, LIAS, LIPT1, DLD, DLAT, and PDHB acted as a low-risk indicator in Lymphoid neoplasm diffuse large B-cell lymphoma (DLBC)." (PMID 36105090, 2022).
endometrial carcinoma (2 papers, 2022). A malignant tumor arising from the epithelium that lines the cavity of the uterine body. "The expression of LIPT1 was positively correlated with CD8 T cells and macrophages in Uterine Corpus Endometrial Carcinoma." (PMID 36276092, 2022).
gastric cancer (2 papers, 2022 to 2025). A primary or metastatic malignant neoplasm involving the stomach. "In addition, high LIPT1 expression was significantly associated with increased DMFS in ovarian cancer (p = 0.013) and decreased post progression survival (PPS) in gastric cancer (p = 0.00077)." (PMID 36330439, 2022).
lung adenocarcinoma (2 papers, 2022 to 2023). A carcinoma that arises from the lung and is characterized by the presence of malignant glandular epithelial cells. "And we found the obvious effect of LIPT1 expression on the patients’ stages in BRCA, TGCT, BLCA, THCA and lung adenocarcinoma (LUAD)." (PMID 36330439, 2022).
osteoporosis (2 papers, 2023 to 2025). A condition of reduced bone mass, with decreased cortical thickness and a decrease in the number and size of the trabeculae of cancellous bone (but normal chemical composition), resulting in increased fracture incidence. "It showed that in osteoporosis patients, CP (P < 0.01), LIPT1 (P < 0.05), SLC25A3 (P < 0.001), and UBE2D3 (P < 0.01) were upregulated, while the expression levels of CDKN2A (P < 0.05), DBH (P < 0.01), DLST (P < 0.05), LOXL2 (P < 0.05), SLC31A1 (P < 0.05), and UBE2D1 (P < 0.01) were downregulated." (PMID 40980812, 2025). "In short, LIPT1 may be involved in osteoporosis by participating in the tricarboxylic acid cycle and affecting mitochondrial energy metabolism." (PMID 37214253, 2023). "LIPT1 may be involved in osteoporosis by participating in the tricarboxylic acid cycle and affecting mitochondrial energy metabolism." (PMID 37214253, 2023).
pancreatic adenocarcinoma (2 papers, 2022). "DLAT, LIPT1, and LIAS served as diagnostic biomarker in pancreatic adenocarcinoma." (PMID 36703728, 2022). "We found a positive correlation between the infiltration of B cells and LIPT1 expression in BLCA, ESCA, pancreatic adenocarcinoma (PAAD) and TGCT." (PMID 36330439, 2022).
pulmonary fibrosis (2 papers, 2022 to 2023). Chronic progressive interstitial lung disorder characterized by the replacement of the lung tissue by connective tissue, leading to progressive dyspnea, respiratory failure, or right heart failure. "In the mouse model of pulmonary fibrosis induced by bleomycin, the genes related to cuproptosis promotion, such as Fdx1, Lias, Dld, Pdha1, Pdhb, Dlat, and Lipt1, were gradually down-regulated in the process of fibroblast differentiation from resting fibroblast to myofibroblast." (PMID 36601107, 2022). "It’s reported that the CRGs, such as FDX1, LIAS, DLD, PDHA1, PDHB, DLAT, and LIPT1, were down-regulated in the lung tissues of pulmonary fibrosis mouse model, and the same results were obtained via analysis of lung tissues scRNA-seq data for human pulmonary fibrosis." (PMID 37266442, 2023).
Cerebral ischemia (1 paper, 2024). Restriction of arterial blood supply to the brain associated with insufficient oxygenation to support the metabolic requirements of the tissue. "Eight hub genes (FDX1, LIPT1, LIAS, DLD, PDHA1, DLAT, PDHB, and GLS) were identified as potential core targets of cerebral ischemia." (PMID 39360273, 2024).
chronic pharyngitis (1 paper, 2025). "LIPT1: schizophrenia and other psychotic disorders, chronic pharyngitis, and nasopharyngitis." (PMID 40149491, 2025).
colitis (1 paper, 2025). Inflammation of the colon. "Notably, when FDX1, LIPT1, and SLC25A3 are considered as potential drug targets, there is a concerning likelihood that they may precipitate an accelerated onset of colitis and depression." (PMID 40149491, 2025).
COVID-19 (1 paper, 2023). A disease caused by infection with severe acute respiratory syndrome coronavirus 2. "Except for LIPT1, COVID-19 patients had significantly higher expression levels of the other eleven CRGs." (PMID 37533853, 2023).
Crohn disease (1 paper, 2024). A gastrointestinal disorder characterized by chronic inflammation involving all layers of the intestinal wall, noncaseating granulomas affecting the intestinal wall and regional lymph nodes, and transmural fibrosis. "Moreover, compared to healthy controls, serum copper levels were higher, but LIPT1 levels were lower in patients with Crohn’s disease." (PMID 39652607, 2024).
endometriosis (1 paper, 2022). The growth of functional endometrial tissue in anatomic sites outside the uterine body. "As expected, the expression of CDKN2A was upregulated, whereas the expression of GLS and LIPT1 was downregulated in UCEC cells versus normal human endometriosis cells." (PMID 35937995, 2022).
Epileptic encephalopathy (1 paper, 2022). A condition in which epileptiform abnormalities are believed to contribute to the progressive disturbance in cerebral function. "A LIPT1 deficiency has been reported in a case of early infantile epileptic encephalopathy." (PMID 36061196, 2022).
liver disease (1 paper, 2023). "Taken together, these five crucial genes, except LIPT1, contribute to the progression and development of liver disease or HCC." (PMID 37124062, 2023).
lung squamous cell carcinoma (1 paper, 2022). "Our analysis results displayed that promoter methylation levels of LIPT1 were significantly reduced in several tumor tissues, including BLCA, lung squamous cell carcinoma (LUSC), rectum adenocarcinoma (READ), THCA, HNSC, CESC, prostate adenocarcinoma (PRAD), UCEC, LUAD, and KIRP." (PMID 36330439, 2022).
lymph node metastasis (1 paper, 2022). "ATP7A (P = 0.007), LIPT1 (P = 0.009), DLAT (P = 0.006) and NDOR1 (P = 0.039) expression were remarkably interrelated to lymph node metastasis (N classification)." (PMID 36313717, 2022).
maturity onset diabetes (1 paper, 2024). "The results indicated that BCL2 and LIPT1 were enriched in pathways such as neuroactive ligand receptor interaction, maturity onset diabetes of the young and RNA degradation." (PMID 39730319, 2024).